CD4 (CD4 molecule)
Diseases named in the same sentence as CD4 in open-access papers (continued):
Sharing a sentence is not in itself a finding about the gene and the disease.
glioma (continued). "Analysis conducted on samples retrieved from the TCGA database revealed a significant increase in the proportion of neutrophils, resting memory CD4+ T cells, regulatory T-cells (Tregs), and M2 macrophages in the high-immunity group of glioma patients." (PMID 36275718, 2022). "In contrast, in low-grade gliomas, the infiltration level of B cells, dendritic cells, macrophages, neutrophils, and CD4+ T cells was significantly correlated with CNPY4 expression." (PMID 35984129, 2022). "scSEQ analysis of the cohort of human glioma samples (resolution = 0.15) identified 11 clusters: polarized microglia; micro-APCs (CD4) and APCs (lipid); T cells; macrophages and NK cells; DCs; neutrophils; and ILCs, immature myeloid cells, and B cells." (PMID 35653194, 2022). "We have confirmed previously reported deficits in circulating CD4 T cell levels among glioma subjects prior to chemoradiation; 11.8% of our training population demonstrated <200 CD4 T cells/μl." (PMID 36127421, 2022). "The results show that SDC1 is associated with the immune infiltration of glioma in the TME, especially activated CD4+T cells and CD8+T cells." (PMID 35669186, 2022). "Using MIS, we observed a significantly positive correlation of gp96 expression with the infiltration levels of CD8+ and CD4+ GITs in grade II-IV gliomas." (PMID 35794988, 2022). "Patient age, CD4+ T cell density, and HDAC3 and HDAC4 mRNA expression were associated with high-grade glioma prognosis." (PMID 35359455, 2022). "FACS-sorted GFP+CD45+CD3+CD4+ TILs from S100a4+/− or S100a4−/− host gliomas were co-cultured with naïve B6 wild-type splenocytes and secreted IFN-γ in the conditioned media was measured by ELISA." (PMID 35140215, 2022). "In glioma patients, a loss of the GNG12 copy number resulted in decreased infiltration of CD4+ T cells, macrophages, neutrophils, and dendritic cells." (PMID 35928884, 2022). "The results of IHC showed that compared with the normal brain tissues, Foxp3+ cells (Foxp3+Treg/CD4+ T cells) were increased significantly in the glioma tissues while T-bet+ cells (T-bet+Th1/CD4+ T cells) were significantly reduced." (PMID 35181676, 2022). "CD4 T cell infiltration-positive Glioma patients have better overall survival compared with CD4 T cell-infiltration negative." (PMID 36138874, 2022). "Meanwhile, analysis of the cellular composition showed that enrichment of M2 macrophages in glioma TME were much more evident than that of the resting memory CD4+ T cells, as supported by the result of cell type-specific expression analysis." (PMID 35350788, 2022). "The results showed that GNG12 is associated with the infiltration of various immune cells in gliomas, especially B cells, CD4+ T cells, macrophages, and dendritic cells in low-grade gliomas." (PMID 35928884, 2022). "Similar to a study on glioma, a significant association was found between COPB2 expression and both CD8+ and CD4+TILs in cSCC tissues." (PMID 35454945, 2022). "Prostaglandin E2 (PGE2) from glioma cells was observed to boost the production of IL-10 by DCs, resulting in the development of a regulatory response in CD4 T cells and a reduction in effector lymphocyte stimulation." (PMID 35269652, 2022). "Compared with normal tissues, Cd4, Spp1 and Col3a1 expression were significantly increased in glioma tissues (Cd4, p < 0.05; Spp1, p < 0.05; Col3a1, p < 0.05), but their expression levels were not correlated with overall survival." (PMID 36147842, 2022). "The accumulation of CD4+CD25+Foxp3+ Tregs is one of the hallmark features of GBM, and Tregs have been the predominant targets for immunotherapy in glioma models and patients." (PMID 35029050, 2022). "Consistent with previous studies, increased CD4+ and PD-1+ cells both predicted worse outcomes in all glioma patients." (PMID 35794988, 2022).
glioma (continued). "Here, using the CIBERSORT algorithm and TIMER web portal, we first report that high hepcidin expression in glioma correlated with the increased infiltration of B cells, CD4+ T cells, CD8+ T cells, neutrophils, macrophages, and dendritic cells." (PMID 36237302, 2022). "In this study, we observed that DUSP10 expression in glioma correlated positively with the abundance of B cells, CD4+ T cells, CD8+ T cells, neutrophils, macrophages, and dendritic cells." (PMID 36713584, 2022). "In glioma, the percentages of CD4+ tumor-infiltrating T lymphocytes rose as tumor grade increased, respectively 39% in WHO grade II, 73% in WHO grade III, and 98% in grade IV." (PMID 35269652, 2022). "Glioma patients who used DEX had the lowest CD4 T, CD8 T, B, NK, monocyte and total lymphocyte cell fractions as well as CD4/CD8 ratio and LMR, and the highest neutrophil fractions and NLR." (PMID 35716311, 2022). "Biological processes show that ITGB2 has involved glioma immune-related activities, especially closely related to B cells, CD4+Tcells, macrophages, neutrophils, and dendritic cells." (PMID 36714574, 2022). "In CGGA, IDH1mt-glioma tissues with high-risk scores had higher memory B cells, CD8 T cells, M1 macrophages, M2 macrophages, and resting dendritic cells and lower M0 and CD4 naïve T cells." (PMID 36159801, 2022). "We observed that CD4+ PD-1+ GITs were accumulated in the regions surrounding gp96+ glioma cells, whereas CD4+ PD-1− GITs were relatively evenly distributed across the tumor tissues." (PMID 35794988, 2022). "FLT3LG seems to exert its anti-tumor activity in conjunction with macrophages and CD4 + T-cells in glioma, supporting the observation of a specific immune-modulatory effect of CIR." (PMID 35158950, 2022). "We next assessed the functional contributions of CD8 and CD4 T cells to therapeutic efficacy by implanting glioma-derived cells in parallel into syngeneic and immunocompromised mice." (PMID 36113478, 2022). "In line with the literature, patients with high grade gliomas in our study exhibit a decreased frequency of CD3+/CD4+ T cells." (PMID 34079819, 2021). "In addition, the risk-score signature was positively associated with malignancy of gliomas and the abundance of tumor-infiltrating immune cells such as macrophages M0 and regulatory T cells (Tregs), but negatively associated with the abundance of monocytes, NK cell activation and T cell CD4+ naive." (PMID 35118063, 2021). "HDAC1 was manifested to serve as a prognostic biomarker for glioma, and an indicator for neutrophil and CD4+ T cell infiltration in LGG." (PMID 34540896, 2021). "To further test the correlation between SERPINA3 mRNA expression and the tumor immune infiltrating of CD4+ T cell in tissues, we performed the IHC experiment in 20 gliomas." (PMID 34449972, 2021). "One retrospective study analyzing 284 gliomas of different grades identified a high CD4+/CD8+ ratio as predictive of poor overall survival, and regulatory T cells (Tregs) being present in high-grade but not in low-grade gliomas." (PMID 34359621, 2021). "Our results from the CIBERSORT analysis confirmed the notion that glioma cells were enriched by the secretion of immune cells, such as leukocytes, CD4+T cells, and Tregs." (PMID 34631528, 2021). "The mRNA expression of ERBB3 and ERBB4 in gliomas was notably positively correlated with the level of CD4+ T cell infiltration (ERBB3, r = 0.1200, p = 0.0016, ERBB4, r = 0.09663, p = 0.0114)." (PMID 33892666, 2021). "CD8+ cytotoxic T lymphocytes (CTLs) and CD4+ CD25+ FOXP3+ regulatory T cells (Tregs) are active lineages of glioma-infiltrating T lymphocytes." (PMID 34211978, 2021). "In IL-12-treated gliomas, we observed an increased frequency of CD4+ T cells and a decrease in frequency and counts of Treg cells." (PMID 33469002, 2021).
glioma (continued). "Standing in as infiltrative T cells are CD4+ helper T cells (Th), CD8+ cytotoxic T cells, and CD4+/CD25+/FoxP3+ Tregs which lead an exhausting life in the suppressive microenvironment of glioma." (PMID 34671362, 2021). "CD4+ and CD8+ tumor infiltrating lymphocytes (TILs) have been well documented in gliomas as a predictor of post-treatment patient outcomes and high percentages of CD4+ and CD8+ TILs have been correlated with the presence of PsP." (PMID 33726710, 2021). "In a rat glioma model, metronomic temozolomide selectively and significantly decreased the Treg/CD4+ ratio in the spleen." (PMID 34771577, 2021). "The expression of MAP3K8 was positively correlated with immune infiltration, including effector memory CD4+ T cells, plasmacytoid dendritic cells, neutrophils, myeloid dendritic cells, mast cells, and macrophage in glioma." (PMID 35004849, 2021). "Among MDSCs, PMN-MDSCs induced CD4+ glioma-infiltrating T lymphocytes to express PD-1, exhibiting more prominent T cell suppression." (PMID 34211978, 2021). "Additionally, follicular helper T cells (Tfh), which are a subset of CD4+ T cells and capable of inducing the differentiation of B cells into plasma cells and memory cells, were found to have a higher level of infiltration in gliomas from the low-risk group of patients." (PMID 34650975, 2021). "Compared to gliomas with wtIDH1/2, IDH-mutated gliomas show small numbers of tumor-infiltrating CD4+ and CD8+ T cells and a low expression of cytotoxic T-lymphocyte–associated genes and IFN-γ–inducible chemokines, including CXCL10." (PMID 34203535, 2021). "The expression level of EGFR mRNA was notably negatively correlated with the infiltration level of DCs (r = − 0.09997, p = 0.0088) and CD4+ T cells (r = − 0.1143, p = 0.0027) in glioma tissue." (PMID 33892666, 2021). "In a murine glioma model, standard treatment with temozolomide promoted the exhaustion of CD4+ and CD8+ T-cell and an increase in Treg and MDSC levels." (PMID 34771577, 2021). "In glioma patients, there is an increased proportion of immunosuppressive Tregs within the remaining CD4 + cell pool in blood, and a prominent infiltrating Treg population within GBM tumor tissue." (PMID 32003759, 2020). "In previous studies, glioma cells were found to be able to produce numerous cytokines, which contribute to the infiltration of different types of immune cells, such as CD4+T cells, CD8+T cells, Tregs, NK cells, TAMs, MDSCs, and neutrophils, into the tumor." (PMID 32678519, 2020). "Our data, in addition to supporting the role of CD4+ T-cells following treatment, highlight the importance of effector and effector memory CD4+ T-cells following glioma reoccurrence." (PMID 33002018, 2020). "In the glioma subtypes identified here, the distribution of immune checkpoint genes was comparable to that of immune cells, including CD4+ T cells, activated CD8+ T cells, B cells, macrophages, dendritic cells, and neutrophils." (PMID 33425739, 2020). "Our study profiled the composition of the TIME in DA and confirmed the presence of immune cells, such as glioma-associated microglia/macrophages (GAMs), CD8+ T cells, CD4+ T cells, regulatory T cells (Tregs), and natural killer cells." (PMID 32117733, 2020). "We found only few CD20+ B lymphocytes and CD4+/CD8+ T lymphocytes in gliomas, both of which occurred primarily within perivascular spaces and around areas of necrosis." (PMID 32528967, 2020). "Using fresh ex vivo gliomas and peripheral blood, the immune cell populations, including both CD4+ and CD8+ T cells and CD11b+ myeloid cells, were isolated and subsequently evaluated using flow cytometry." (PMID 32721947, 2020). "Log-rank analysis of the Kaplan-Meier survival curves was consistent with the results predicted by TCIA, further demonstrating the functions of central memory CD4 T cells and NK cells in patients with glioma." (PMID 31451090, 2019).
glioma (continued). "Immunohistochemical staining was performed to examine the expression of central memory CD4 T cells and NK cells in 30 glioma samples from patients." (PMID 31451090, 2019). "The presence of CD8+ T cells was shown to reduce tumorigenicity when CD4+ or NK+ cell-depleted mice had been immunized with IL-7-producing glioma cells." (PMID 31649684, 2019). "We also performed immunohistochemical staining of immune cell-specific markers including CD11b, CD14, CD56, CD11c, FOXP3, CD8 and CD4 in glioma tissues." (PMID 31377744, 2019). "The glioma microenvironment is infiltrated with small numbers of T lymphocytes, mostly CD4+ T helper (Th), CD8+ T cytotoxic (Tc), and CD4+CD25highFoxP3+ Treg cells." (PMID 31225500, 2019). "In line with this, a previous report has indicated that not only the number of T-cells but also their balance determines effective anti-tumor immunity, in particular high CD4+/CD8+ ratios contribute to poor prognosis of glioma patients." (PMID 30972297, 2019). "PD-L1 expressed in glioma cells was shown to strongly inhibit CD4+ and CD8+ T-cell activation through interaction with PD-1 on T cells." (PMID 31225500, 2019). "Secondly, in a study with 52 glioblastoma patients, it was shown that there is a correlation between the number of PMN-MDSCs and CD4+ effector memory T-cells (CD4+ Tem) within the gliomas." (PMID 31225500, 2019). "Antitumor efficacy of D2C7-IT was examined in immunocompetent, intracranial murine glioma models and the role of T cells was assessed by CD4+ and CD8+ T cell depletion." (PMID 31142380, 2019). "Siglec-F, inhibitory CD33-related sialic acid receptor, is highly expressed on murine eosinophils, macrophages and CD4-positive T cells, which are a part of complex glioma microenvironment." (PMID 30443853, 2019). "In the case of GL26 glioma tumors, T+H treatment triggered ~20–50% increase in CD4+ T cell infiltration, compared to TMZ or HOE642 monotherapy alone." (PMID 30262908, 2018). "In particular, a high CD4+/CD8+ ratio has been associated with poor outcome in colorectal carcinoma and glioma, and favorable disease outcome in mesothelioma patients." (PMID 30216999, 2018). "Flow cytometry analysis of glioma-infiltrating immune cells showed that PD-1 expression on both CD4+ and CD8+ T cells gradually increased as tumor progressed, and non-inoculated brain was used as normal tissue." (PMID 30333036, 2018). "In the GL261 glioma model, we found that the expression of PD-1 was elevated in both CD4+ and CD8+ T cells." (PMID 30333036, 2018). "In glioma patients the accumulation of CD4+/CD8+ T cells and Treg expressing high levels of CTLA-4 and PD-1, or the high expression of PD-L1 in glioma cells correlates with WHO high grade and short survival." (PMID 30406030, 2018). "Tumor-infiltrating immune cells of glioma patients exhibit significant expression of CTLA-4 (particularly for CD4+ effector T cells and Tregs)." (PMID 30619286, 2018). "Functionally, PD-1 expression is closely related to the defects of IFN-γ production from glioma-infiltrating CD4+ effector memory T cells." (PMID 27756892, 2017). "We isolated the effector T cells (Teff cells; CD4+ CD25− T cells) from the glioma tissue and the spleen of mice." (PMID 28002799, 2017). "Our data suggest that CD4+ and perivascular Foxp3+ TILs impact angiogenesis and tumor recurrence in patients with gliomas." (PMID 29163521, 2017). "Supporting this, activated CD4+ T cells have been demonstrated to sensitise cervical cancer and glioma cells to the effects of γ-radiation in vitro, supporting a role for CD4+ T cells in the tumor response to radiation." (PMID 28002789, 2017). "When co-cultured with T cells, glioma-derived MDSCs can up-regulated PD-1 expression on CD4+ T effector memory T cells." (PMID 27756892, 2017). "CD4/25-positive Tregs have been previously shown to play a critical role in glioma-related immune surveillance." (PMID 27585656, 2016).
glioma (continued). "While early characterizations of glioma tissue noted dramatic CD4+ lymphopenia and T cell anergy, the mechanisms by which gliomas achieved global immunocompromise were not yet known." (PMID 26881264, 2016). "Enhancing the presentation of tumor antigens has been proposed as a viable therapy option, and peptide-based glioma vaccine was successfully developed to activate the MHC class II molecules-dependent CD4+ T cells." (PMID 27835581, 2016). "TGF-β is an essential glioma-derived cytokine that specifically represses the proliferation of antigen-specific CD4+ T cells." (PMID 26291724, 2015). "Combination therapy with 4-1BB activation and CTLA-4 blockade in the setting of focal radiation therapy improves survival in an orthotopic mouse model of glioma by a CD4+ T cell dependent mechanism and generates antigen-specific memory." (PMID 25013914, 2014). "Consistent with this notion, IL-10-producing CD4+ cells have been demonstrated to effect tumor rejection in a murine glioma model by augmenting CTL and NK cell response." (PMID 23874336, 2013). "DSP1–7 was stably expressed in the glioma-derived NP-2 cell lines, which expressed CD4/CXCR4 (N4X4) or CD4/CCR5 (N4R5), respectively." (PMID 24050252, 2013). "ESR1 binding sites were significantly enriched for DNaseI hypersensitivity peaks drawn from multiple cell types (Ecc-1, Ishikawa, MDF-7, T47D, LNCaP, HUVEC, glioma and Th1 CD4+)." (PMID 24171864, 2013). "CD4+FoxP3+ Tregs in gliomas have been shown to express a variety of immuno-regulatory molecules, such as CD25, CTLA-4, GITR (glucocorticoid-induced TNFR family related gene), and CXCR4 at high levels." (PMID 24202450, 2013). "In this report we investigated the ability of five candidate peptide epitopes derived from glioma-associated antigens MAGE and IL-13 receptor α2 to detect and characterize CD4+ helper T cell responses in the peripheral blood of patients with malignant gliomas." (PMID 23186108, 2012). "GBM also elicits an adaptive immune response and there is an increased infiltrate of CD4+FoxP3+ regulatory T cells in GBM relative to lower-grade gliomas and normal brain." (PMID 22937035, 2012). "For example, immune infiltration of gliomas was recognized as one of the processes following the development of advanced gliomas, and it has been demonstrated that gliomas are infiltrated by microglia, CD4 and CD8 T lymphocytes, and natural killer (NK) cells." (PMID 21949886, 2011). "In a humanized SCID mouse model, CD4+ T cells were isolated from a mouse that was actively rejecting a membrane isoform of macrophage colony stimulating factor (mM-CSF) transduced U251 glioma." (PMID 21437175, 2010). "Flow cytometry was used to determine transduction efficiencies in NP2/CD4/CXCR4 (glioma cell line stably transduced with the HIV receptors) and HeLa/CD4 cell lines." (PMID 20929586, 2010). "But no exact mechanisms were provided in these last studies, explaining how the direct beneficial role of CD4+ T cells occurred in these glioma models other than by the “classic” T-helper cell function." (PMID 21437175, 2010). "In the rat 9L (also known as T9) glioma model, effective immunity was seen by the adoptive transfer of immunized CD4+ T cells." (PMID 21437175, 2010). "We analyzed the effect of the glioma on the expansion of the populations of CD4+ and CD8+ T cells as well as Tregs in the bone marrow of glioma-bearing mice at three weeks after tumor implantation (three mice per group)." (PMID 20339520, 2009). "FACS analysis revealed an inversion of the CD4/CD8 ratio in untreated glioma-bearing mice, in which case data were 3.14 ± 0.4 (CD4+)/1.80 ± 0.07 (CD8+), giving a ratio of 1.74." (PMID 20339520, 2009). "The intracellular expression of Foxp3 in gated CD4+ T cells from the bone marrow of glioma-bearing mice confirmed the presence of Tregs in 20.0% ± 2.33% of the cells." (PMID 20339520, 2009).